CCNA2 (cyclin A2)
Diseases named in the same sentence as CCNA2 in open-access papers (continued):
Sharing a sentence is not in itself a finding about the gene and the disease.
glioma (continued). "Similarly, high expression of CCNA2 and AURKA was associated with a worse overall survival (OS) of glioma patients." (PMID 30995921, 2019). "Importantly, we found that knock-down of FBXW7 increases the levels of several cell cycle proteins, such as E2F1, LSH, KI67, Cyclin A2 and Cyclin E2, both in basic conditions, as well as in miR-10b – depleted glioma cells." (PMID 25738367, 2015). "Similarly, the increase in cyclin A2/B2 mRNA levels in glioma cells with ORC6 overexpression might also be attributed to an expanded S phase population due to such overexpression." (PMID 38971772, 2024). "ORC6 emerged as a crucial regulator for the expression of key oncogenic genes, including Cyclin A2, Cyclin B2, and DNA topoisomerase II (TOP2A), within glioma cells." (PMID 38971772, 2024). "ORC6 depletion, inhibited proliferation, decreased expression of Cyclin A2/B2/TOP2A, and increased apoptosis were detected within these ORC6 KO intracranial glioma xenografts." (PMID 38971772, 2024). "In contrast, in P1 glioma cells overexpressing ORC6, “oeORC6-Slc1” and “oeORC6-Slc2,” there was a significant elevation observed in both mRNA and protein expression levels of Cyclin A2, Cyclin B2, and TOP2A." (PMID 38971772, 2024). "Here, the observed downregulation in both mRNA and protein levels of Cyclin A2 and Cyclin B2 upon silencing or knocking out ORC6, as well as the increased cyclins expression upon ORC6 overexpression in primary human glioma cells." (PMID 38971772, 2024). "We only observed higher expression of three genes (HMGB2, CCNA2 and CASP3) in the glioma tissues, consistent with the conclusions from the previous analysis based on the TCGA cohort." (PMID 35601497, 2022). "The IHC staining images of HMGB2, CCNA2, and CASP3 demonstrated their differences in protein expression between glioma and normal brain tissues, further supporting the stability of the model." (PMID 35601497, 2022). "The function of fibronectin 1 (FN1), cyclin A2 (CCNA2), and cyclin B2 (CCNB2) in glioma OS has been reported." (PMID 32642801, 2020). "Finally, PI staining flow cytometry, qPCR and WB showed that NaB blocked the cell cycle of glioma cells by downregulating CDC2, CDC25C, CCNA2 and CCNB cell cycle-related proteins." (PMID 40297576, 2025). "Furthermore, BMP2, NCF1, HSPB1, PIGT, PTX3, CCNA2, and CCNB2 exhibited increased expression, while DES displayed decreased expression in glioma tissues." (PMID 40656950, 2025). "Subsequent studies unveiled a significant decrease in the mRNA and protein expression levels of Cyclin A2, Cyclin B2, and TOP2A within koORC6 P1 glioma xenograft tissues, where elevated levels of cleaved-caspase-3, cleaved-caspase-9, and cleaved-PARP-1 were detected, indicating apoptosis activation." (PMID 38971772, 2024). "Besides, the positive correlation between Pontin and six E2F1 targets (AURKA, CDK1, CDK4, CCNA2, CCNB2, E2F8) assessed by GEPIA in glioma further supported the positive regulation of E2F1 targets expressions by Pontin." (PMID 33542204, 2021). "The results showed that hsa-let-7b-5p could regulate target genes, including cell cycle protein A2 (CCNA2), CCNB2, PLK1, and AURKA, and further affect the progress of glioma." (PMID 30995921, 2019). "We then tested whether the temporal patterns of the prioritized 5 genes (i.e., KIF2C, CCNA2, NDC80, KIF11 and KIF23) could be used to predict drug sensitivities of different glioma cell lines." (PMID 31682596, 2019). "However, no research on CCNA2 in glioma has been published, and the process in glioma has to be investigated further." (PMID 35903107, 2022).
glioma (continued). "Therefore, in the current study, the downregulation of cyclin A2, cyclin B3, and CDK1 genes could prompt cell cycle arrest in U87 glioma cells." (PMID 28837560, 2017). "However, CCNA2 mRNA is lower in acute myeloid leukemia (LAML) than that in normal tissues from the GTEx project (p < 0.001), and we do not obtain a significant difference in brain lower grade glioma (LGG) and pheochromocytoma and paraganglioma (PCPG)." (PMID 35480884, 2022).
bladder cancer (34 papers, 2009 to 2025). "We found that TalaA blocked the transition from the G1 to S phase of bladder cancer cells and downregulated CCNA2 and CCNB1, which are well-known therapeutic targets for various cancers." (PMID 37866481, 2023). "To determine the signaling pathway through which PBRM1 mediates cell cycle regulation, we analyzed the protein levels of several cyclins (cyclin A2, D1, D3 and B1) in bladder cancer cells." (PMID 25978027, 2015). "Elevated levels of CCNA2 have been correlated with a poorer prognosis in patients with bladder cancer, indicating that higher expression of this cyclin may be associated with more adverse outcomes and a more aggressive disease course." (PMID 39456780, 2024). "Moreover, CCNA2, a cyclin that functions as a regulator of CDKs, is upregulated in bladder cancer." (PMID 39456780, 2024). "Another experiment also proved that miR-381-3p blocks the dual regulatory role of CCNA2 (Cyclin-A2) in modulating CDK6 and MET-mediated cell-cycle pathway and EMT progression in bladder cancer." (PMID 36856518, 2023). "The regulatory role of CCNA2 in the MET-mediated cell-cycle pathway is reportedly blocked by miR-381-3p, which promotes the proliferation and metastasis of bladder cancer cells." (PMID 34093807, 2021). "In bladder cancer, miR-381-3p has also been found to regulate the cell cycle of bladder cancer cells, increasing apoptosis rate by targeting negative regulation of CDK6, CCNA2, and MET." (PMID 38818039, 2024).
prostate carcinoma (31 papers, 2005 to 2025). A carcinoma that arises from epithelial cells of the prostate gland. "Several data-mining analyses revealed that cyclin A2 is overexpressed in prostate cancer and its overexpression is associated with poor prognosis and short overall cancer survival." (PMID 40391771, 2025). "We selected CCNA2 for further study and found that CCNA2 was significantly associated with biochemical recurrence of prostate cancer." (PMID 31956366, 2020). "CCNA2 was significantly associated with biochemical recurrence, disease-free survival and overall survival rate of prostate cancer." (PMID 31956366, 2020). "We also verified the role of CCNA2 in prostate cancer cell lines and found that CCNA 2 is associated with tumor cell proliferation, invasion, metastasis, and cell cycle." (PMID 31956366, 2020). "Taken together, we used WGCNA and obtain a gene CCNA2 which is significantly associated with the prognosis of prostate cancer, which may be an indicator of the prognosis of prostate cancer and a new therapeutic target." (PMID 31956366, 2020). "In our study, we further found that, compared with primary prostate cancer, the expression levels of CCNA2 and CKS2 in CRPC increased significantly." (PMID 37476415, 2023). "Prostate cancer is considered a continuous progressive disease, and as the disease progresses, CCNA2 and CKS2 increase." (PMID 37476415, 2023). "We studied CCNA2 and found that it has a significant correlation with biochemical recurrence rate and survival rate of prostate cancer." (PMID 31956366, 2020). "Then we used the GEPIA database to study the correlation between CCNA2 expression and prognosis of prostate cancer, the results showed the low CCNA2 expression had meaningful relationship with Overall Survival and Disease-Free Survival." (PMID 31956366, 2020). "In this study, we used the TCGA database and WGCNA to identify a gene CCNA2 that is closely related to tumor progression and the prognosis of patients with prostate cancer." (PMID 31956366, 2020). "Cytological experiments suggest that down-regulation of CCNA2 can inhibit the proliferation, invasion, and metastasis of prostate cancer cells and affect the cell cycle of tumor cells." (PMID 31956366, 2020). "The results showed that for both prostate cancer cell lines C42 and PC3, downregulation of cell CCNA2 expression caused cell cycle changes: more cells were stuck in the S phase." (PMID 31956366, 2020). "Subsequently, we used the CamcApp to study the correlation between the expression of CCNA2 and the biochemical recurrence of prostate cancer." (PMID 31956366, 2020). "The ability of cancer cell proliferation, invasion and metastasis was decreased after down-regulated expression of CCNA2 in prostate cancer cell lines." (PMID 31956366, 2020). "In PC-3 prostate cancer cells, luteolin reduced the transcription of CCNA2 along with that of other cell cycle genes and inhibited the proliferation of those cells." (PMID 23320178, 2012). "Cyclin A2 was suggested to be a biomarker and therapeutic target for advanced prostate cancer." (PMID 40391771, 2025). "Furthermore, R9-AR-PIP and PCNA-I1S reduce cyclin A2 expression in prostate cancer cells expressing both AR-FL and AR-Vs." (PMID 40391771, 2025). "Indeed, knockdown expression of cyclin A2 using siRNA or inhibition of cyclin A2 activity using small molecule were shown to inhibit cell growth, invasion, and migration in several lines of prostate cancer cells." (PMID 40391771, 2025). "Cyclin A2 was reported as an AR-Vs specific target gene in prostate cancer cells." (PMID 40391771, 2025). "CCNA2 was found to contribute to prostate cancer through the modulation of its expression." (PMID 39195643, 2024). "In our study, a machine learning algorithm predicted that CCNA2 may be one of the key driving factors for the transformation of primary prostate cancer to CRPC, and virtual screening predicted that Aprepitant and CCNA2 protein have strong binding ability." (PMID 37476415, 2023).
prostate carcinoma (continued). "In addition, we suppressed the expression of CCNA2 in prostate cancer cell lines via siRNA and found that the proliferation, migration and invasion ability of tumor cells were clearly impaired." (PMID 31956366, 2020). "We first studied the expression of CCNA2 in prostate cancer and adjacent tissues." (PMID 31956366, 2020). "In this study, the transcriptome data of prostate cancer on TCGA was analyzed by weighted gene co-expression network, and the gene with a significant correlation with disease Gleason stage and tumor T stage was identified: CCNA2." (PMID 31956366, 2020). "This also suggests that CCNA2 might be a target for the treatment of prostate cancer and will have a high clinical significance." (PMID 31956366, 2020). "The study proved CCNA2 is a potential predictor of prostate cancer progression and prognosis and might be an excellent potential therapeutic target." (PMID 31956366, 2020). "Therefore, we speculate that CCNA2 and CKS2 may be critical factors for the deterioration of prostate cancer, serving as new diagnostic biomarkers and therapeutic targets for CRPC." (PMID 37476415, 2023). "Although it was reported that CCNA2 is an AR-Vs specific or target gene in prostate cancer cells, our finding reveals that dihydrotestosterone increases the ARE occupancy by AR-FL in CCNA2 gene and cyclin A2 expression in AR-FL positive cells." (PMID 40391771, 2025). "Through validation with training and testing cohorts, we found that CCNA2 and CKS2 significantly differed in expression levels between primary prostate cancer and CRPC." (PMID 37476415, 2023). "The expression of CCNA2 and CKS2 in the training cohort CRPC samples was significantly higher than that in the primary prostate cancer samples (p < 0.001)." (PMID 37476415, 2023). "We cultured prostate cancer cell lines C42 and PC3 and down-regulated the expression of CCNA2 by siRNA to observe the effect of CCNA2 on cancer cells." (PMID 31956366, 2020). "In particular, both the CCNA2 gene and FAS gene are activated by the androgen receptor that is the therapeutic target of prostate cancers." (PMID 32164534, 2020). "In prostate cancer PC-3 cells, silencing ANO1 reduced the expression of cyclin D1 (CCND1), cyclin A2 (CCNA2), CDK1 and CDK2." (PMID 27732935, 2016). "Interestingly, previous studies found that CCNA2 and CKS2 were highly expressed in primary prostate cancer compared to normal prostate cancer tissues." (PMID 37476415, 2023). "Discussion: The expression of CCNA2 and CKS2 increases with the progression of prostate cancer, which may be one of the driving factors for the progression of prostate cancer and can serve as diagnostic biomarkers and therapeutic targets for CRPC." (PMID 37476415, 2023). "Data from the Tomlins prostate cancer dataset in Oncomine showed that the mean expression of CCNA2 in prostate cancer was 0.9, and the expression level in normal glandular prostate was -0.81, the difference was statistically significant (P< 0.01)." (PMID 31956366, 2020).
cervical carcinoma (28 papers, 2006 to 2025). A carcinoma arising from either the exocervical squamous epithelium or the endocervical glandular epithelium. "This protein binds and activates cyclin-dependent kinase 2 and thus promotes transition through G1/S and G2/M.It was reported that CCNA2 was up-regulated and the high CCNA2 expression promoted cell cycle progression in cervical cancer." (PMID 39060960, 2024). "The antibody CAB000114 was used to detect CCNA2 at medium intensity with the proportion of stained cells < 25% in normal cervix tissue, and it showed high intensity staining in cervical cancer tissue, with the proportion of stained cells from 25 to 75%." (PMID 39060960, 2024). "The TOP2A, AURKA and CCNA2 in cervical cancer were significantly increased, while IVL, KRT1, and IGFBP5 were significantly decreased, compared with normal tissues, which was consistent with the screening results." (PMID 39060960, 2024). "Research has shown that CCNA2 is significantly increased in cervical cancer tissues, suggesting a possible mechanism of anomalous mitosis in this condition." (PMID 38972247, 2024). "The results suggest that KLF14 promoted JNK-pathway activation to induce S-phase arrest and promote the expression of CDK2 and CCNA2 in cervical cancer cells." (PMID 38143751, 2023). "ESRP1 was shown to induce G1-phase cell cycle arrest and suppress cell proliferation in cervical cancer cells by decreasing cyclin A2 mRNA stability through the direct binding to the 3’ UTR of cyclin A2." (PMID 38110955, 2023). "Epithelial splicing regulatory protein 1 (Esrp1) overexpression induces G1-phase cell cycle arrest by downregulating cyclin A2 expression and inhibits the proliferation of cervical carcinoma cells." (PMID 36880057, 2023). "ESRP1 promoted cell cycle G1-phase arrest and inhibited cell proliferation in cervical carcinoma cells by downregulating cyclin A2 protein levels." (PMID 38110955, 2023). "This study provides the first evidence that ESRP1 overexpression induces G1-phase cell cycle arrest via reducing the stability of the cyclin A2 mRNA, and inhibits cervical carcinoma cell proliferation." (PMID 31362365, 2019). "This study demonstrated that Ary can restrict cervical cancer cells in G1/S phase along with cyclin A2 and Cdk2 expression increase." (PMID 27259234, 2016). "Overall, these data suggested that the activation of cyclin A2/CDK2 by HDAB contributed to S phase arrest in cervical cancer cells." (PMID 26041102, 2015). "HDAB treatment of cervical cancer cells resulted in S phase arrest and apoptosis, together with cyclin A2 and CDK2 upregulation." (PMID 26041102, 2015). "The results showed that the expression of TOP2A, AURKA and CCNA2 were statistically increased in cervical cancer cell, while the expression of IGFPB5 was statistically decreased in cervical cancer cell, which was consistent with the results of GEO dataset and TCGA database." (PMID 39060960, 2024). "The results of the present study further showed that KLF14 induces S-phase arrest in cervical cancer and activates the JNK pathway to promote the expression of CDK2 and CCNA2 in cervical cancer cells, with its zinc fingers participating in the induction of S-phase arrest." (PMID 38143751, 2023). "Subcutaneous xenograft studies to explore the effects of KLF14 on cervical cancer cell proliferation in vivo, and western blotting was implemented to measure the expression of CCNA2, CDK2, and the activation levels of the MAPK-signaling pathway proteins in tumours." (PMID 38143751, 2023). "The findings suggest that the ESRP1/cyclin A2 regulatory axis may be essential as a regulator of cell proliferation, and may thus represent an attractive target for cervical cancer prevention and treatment." (PMID 31362365, 2019). "Taken together, these data suggested that the ESRP1 may induce G1-phase arrest in human cervical cancer cells by downregulating cyclin A2 expression." (PMID 31362365, 2019).
cervical carcinoma (continued). "Repression of cyclin A2 expression has been reported to result in cycle G1-phase arrest, and cyclin A2 siRNA treatment is known to result in cell cycle G1-phase arrest in HeLa cervical cancer cells, as was confirmed in our experiments." (PMID 31362365, 2019). "The expression of these hub genes were verified through TCGA, GEPIA, qRT-PCR, and immunohistochemistry, and it was found that TOP2A, AURKA as well as CCNA2 were overexpressed and IGFBP5 was low expression in cervical cancer." (PMID 39060960, 2024). "TOP2A, AURKA and CCNA2 were overexpressed in cervical cancer, while IVL and IGFBP5 were low expression in cervical cancer." (PMID 39060960, 2024). "Vivo experiments revealed that KLF14 inhibited cervical cancer cell proliferation (P<0.01) and that p-JNK/JNK, CDK2, and CCNA2 expression levels were augmented in tumours in the overexpression group (P<0.01)." (PMID 38143751, 2023). "Cervical cancer cells were treated with JNK-pathway inhibitors/agonists before we assessed changes in the cell cycle and the expression of the CDK2, CCNA2, and p-JNK/JNK." (PMID 38143751, 2023). "Functional enrichment analyses and gene set enrichment analyses indicated that high mRNA expression of cyclin A2 (CCNA2) and cyclin-dependent kinase 2 (CDK2) stimulated cell cycle progression in cervical cancer." (PMID 35246013, 2022). "The gene set enrichment analysis results of CCNA2 and CDK2 indicated that high mRNA expressions of CCNA2 and CDK2 stimulate cell cycle progression in cervical cancer." (PMID 35246013, 2022). "It was found that TOP2A, AURKA, CCNA2 and IGFBP5 could be all potential tumor markers for cervical cancer." (PMID 39060960, 2024). "This study showed that TOP2A, AURKA, CCNA2 and IGFBP5 screened through bioinformatics analysis were significantly differentially expressed in cervical cancer samples compared with normal samples, which might be biomarkers of cervical cancer." (PMID 39060960, 2024). "Moreover, we evaluated the expression of cell cycle-related genes (CCNA2, MCM2 and SKP2) in cervical cancer cells transfected with siNC or siACTL6A." (PMID 34395295, 2021). "Another cervical cancer study showed that miR-497-5p inhibits cell proliferation through CBX4 targeting, which resulted in cell cycle arrest at the S phase and decreased expression of CDK2 and cyclin A2 proteins." (PMID 33374439, 2020). "However, unexpectedly, the attenuation of S phase arrest by cyclin A2 siRNA and flavopiridol further promoted the HDAB-induced apoptosis and colony formation inhibition in cervical cancer cells." (PMID 26041102, 2015). "However, interestingly, the TCGA database and GEPIA online website analysis showed that TOP2A, AURKA, CCNA2 and IVL were overexpressed and IGFBP5 was low expression in cervical cancer, and there was no statistical difference in the expression of KRT1 in cervical cancer tissue and normal tissue." (PMID 39060960, 2024).